ZEB1 (zinc finger E-box binding homeobox 1)
Diseases named in the same sentence as ZEB1 in open-access papers (continued):
Sharing a sentence is not in itself a finding about the gene and the disease.
tumor (continued). "Finally, it has been demonstrated that lncRNA HOXC-AS2 induces ZEB1 by sponging miR-876-5p, leading to the stimulation of EMT and enhanced migration and invasion of tumor cells." (PMID 32664703, 2020). "A xenograft tumor model in nude mice was established to probe further how LINC00152 could promote EMT and resistance of EC cells to L-OHP treatment via the EZH2/ZEB1 axis." (PMID 33292221, 2020). "While cell lines preferentially adopt either a proliferative or an invasive phenotype, with a clear-mirrored expression of ZEB1 and MITF, tumors in vivo display a higher level of intra-tumor heterogeneity with a significant proportion of cells in the mixed/intermediate state." (PMID 32759677, 2020). "For example, the expression of tumour suppressor miRNA-34a is usually relatively low in various cancers, such as PC, NSCLC, and ALL, and it has been identified as a tumour suppressor with multiple targets, including CD44, PD-L1, ZEB1, and BCL-2." (PMID 32340605, 2020). "The mechanism may be related to the regulation of the miR-200c/ZEB1 axis through the generation of ROS induced by UTMD, which may provide a new strategy to prevent the tumor cells EMT under UTMD treatment." (PMID 32313093, 2020). "Importantly, ZEB1 was found to be a target of miR-873, and that increasing miR-873 expression down-regulates the expression of YAP and ZEB1, and sensitizes tumor cells into gemcitabine therapy." (PMID 32664703, 2020). "Among them, zinc finger E-box binding homeobox-1 (ZEB1) and -2 (ZEB2) are molecules that play vital roles in signaling pathways to ensure the survival of tumor cells, particularly through enhancing cell proliferation, promoting cell migration and invasion, and triggering drug resistance." (PMID 32664703, 2020). "Notably, the expression and localization of TAZ and ZEB1 were heterogeneous—the center of the tumor masses was less stained than the periphery, where an overexpression of both TAZ and ZEB1 was noted." (PMID 32545795, 2020). "Hence, ZEB1 and ZEB2 were more frequently expressed in tumor tissue as compared to PT tissue or tissue of CP and HCs." (PMID 32630552, 2020). "Notably, tumor sections from fatostain-treated mice showed a significantly lower staining of SREPB1, ZEB1, and vimentin, while also showing increased E-cadherin, agreeing with the in vitro observations." (PMID 31861383, 2019). "The mRNA expression level of ZEB1 was significantly elevated in tumor tissues, related to that in corresponding non-tumor tissues (P < 0.01)." (PMID 31007650, 2019). "However, the depletion of Zeb-1 significantly reduced tumor metastasis in the same KPC model, which suggested various EMT-TFs have different sub-functions of tumor metastasis in cancers." (PMID 30915036, 2019). "ZEB1 expression has been related to early stage IB of NSCLC, tumor-node-metastasis stage, and EMT." (PMID 31867044, 2019). "Tumor cell invasion, dissemination, and metastasis could be triggered by aberrant activation of EMT, and ZEB1 is regarded as a master EMT-TF17,35." (PMID 30674889, 2019). "Moreover, the disseminating tumor cell clusters boost metastatic colonization of the lungs via MET, as exemplified by attenuated ZEB1 expression." (PMID 31331982, 2019). "MiR-101, miR-155-5p, and miR-199b, as tumor suppressors, inhibit EMT by targeting ZEB1." (PMID 30813457, 2019). "In addition to a high percentage of VIM-positive tumour cells, MSCCs had a low percentage of CDH1-positive cells and a high percentage of TWIST1-, ZEB1- and ZEB2-positive cells, characteristic of EMT." (PMID 31080552, 2019). "ZEB1 also has a tumor suppressive role, independent of its ability to induce EMT, given that ZEB1 is able to induce EMT in both KRAS- and EGFR mutant cell lines." (PMID 31867044, 2019). "However, some studies failed in confirming the expression of the classic EMT-related transcription factors ZEB1, TWIST, SNAIL, and SLUG in tumor buds." (PMID 31803624, 2019).
tumor (continued). "To investigate whether ALDH3A1 expression might be involved in mesenchymal phenotype development, we studied EMT markers (CDH1, Zeb1, VIM, and FN1) at the mRNA expression level in all stem-cell-like tumor cells." (PMID 31817719, 2019). "In three out of four lesions the tumor was positive for NFATc2, ZEB1 and N-cadherin, but lacked MITF." (PMID 30710146, 2019). "Notably, ZEB1 interacts with its corepressor CtBP or BRG1 to repress E-cadherin expression, which in turn promotes tumor cell invasion and metastasis." (PMID 31064130, 2019). "In a fourth lesion the tumor expressed NFATc2 and ZEB1, but was negative for N-Cadherin and expressed MITF." (PMID 30710146, 2019). "Immunostaining of paired pre-/post-treatment tumor specimens showed a reduction of β-catenin, CyclinD1, Zeb-1, and c-myc expression, in the absence of N-cadherin modulation." (PMID 31390375, 2019). "The ability of ZEB1 to function as a tumor suppressor or tumor promoter would not be a first within the cancer field." (PMID 32309604, 2018). "More importantly, ZEB1 deletion had a significant and negative effect on tumor progression, invasiveness, and metastasis, reaffirming EMT’s role in PDAC metastasis." (PMID 29373514, 2018). "There was no significant upregulation of ZEB-1 mRNA in PCI-13 cells co-incubated with exosomes as opposed to significant up-regulation of ZEB-1 message in A549 cells indicating variability in responses to exosome uptake by different tumor cells." (PMID 29854876, 2018). "Finally, in multiple breast cancerdatasets, high levels of ESRP1, ESRP1/HAS2, and ESRP1/ZEB1 correlate with poorprognosis, supporting the relevance of ZEB1/ESRP1 and ZEB1/HAS2 axes in tumorprogression." (PMID 31069317, 2018). "Furthermore, the tumor sections were stained for E-cadherin, FN1, ZEB1 and vimentin expression to quantitatively evaluate the EMT associated marker." (PMID 30098599, 2018). "This higher tumor development may be related to higher levels of the EMT transcription factors Snail 2, Zeb1, and Zeb2." (PMID 29949929, 2018). "Moreover, ESRP1 negatively correlated withboth ZEB1 and the extent of EMT across multiple datasets corresponding to invitro experiments and primary tumor samples." (PMID 31069317, 2018). "The wound‐healing assay showed that ZEB1 knockdown significantly reduced PC3 and DU‐145 cells migration, while the Transwell invasion assay showed that the down‐regulation of ZEB1 expression significantly down‐regulated tumour cell invasion capacity." (PMID 29754422, 2018). "The results indicated that EPI effectively inhibited tumor growth in BALB/c nude mice with control tumors but not in the mice with ZEB1-expressing tumors." (PMID 29352223, 2018). "Zeb1, as EMT regulator, plays a well-recognized role in tumor progression and metastasization." (PMID 29599503, 2018). "Tgf-β classically induces Zeb1 to repress epithelial specification genes such as E-cadherin during EMT25,29, implying Tgf-β1 accumulating at sites of tumor formation might be important for driving EMT." (PMID 29930325, 2018). "Additionally, we found that the downstream target genes just like ZEB1 and MMP13, which play an important role in tumour regulation, were decreased in the INTS6 overexpressing cells." (PMID 28899352, 2017). "Tumor cells with EGFR amplification, those in the process of migration or exposed to hypoxia all have been shown to express higher levels of ZEB1 than controls and experimental studies have identified molecular mechanisms involved in ZEB1 regulation, such as PDGFRA, Wnt- or TGF-beta signaling." (PMID 28945795, 2017). "As in non-neoplastic tissue, tumor-infiltrating CD68+ or HLA-DR+ cells were consistently negative for ZEB1, too." (PMID 28945795, 2017). "These signaling events eventually increase the expression of a group of genes such as N-cadherin, vimentin and Zeb1, which trigger metastatic changes including epithelial mesenchymal transition (EMT), enhancement of motility and the invasiveness of tumor cells." (PMID 29133945, 2017).
tumor (continued). "We therefore performed immunofluorescent double labeling of ZEB1 and IDH1 R132H in four IDH-mutant GBM cases and quantified colocalization after blinded manual scoring of individual nuclei from at least three fields of views per tumor." (PMID 28945795, 2017). "Additionally, PVT1 overexpression also increased the expression of BMI1, ZEB1 and ZEB2 in xenograft tumor derived from 786-O cells." (PMID 29156724, 2017). "While all specimens displayed some degree of ZEB1 expression in the stroma, 63 did not express ZEB1 in the epithelial tumour cells, and high levels of stromal ZEB1 correlated with positive staining in the tumour." (PMID 28544627, 2017). "We found widespread expression of ZEB1 in all tumor entities and observed a dichotomous nuclear expression pattern identifying ZEB1-positive and ZEB1-negative populations in all tumors." (PMID 28945795, 2017). "Also, in the animal experiments, PVT1 overexpression increased the expression of BMI1, ZEB1 and ZEB2 in xenograft tumor derived from 786-O cells." (PMID 29156724, 2017). "In addition, EMT involvement in oncogenesis or tumour malignancy is controlled by various EMT regulators, including N-myc, ZEB1/2, Snail, Slug, Twist, SRF, and β-catenin." (PMID 28727734, 2017). "Here we analyzed whether tumor cell secreted HA and HAS2 expression is promoting ZEB1-dependent EMT and found that HA in combination with CD44s activates ZEB1 expression." (PMID 28086235, 2017). "Moreover, ZEB1 expression is high in SHH‐MB and inhibits granular zone exit, which eventually contributes to tumor formation." (PMID 28556516, 2017). "ZEB1 co-expression with TWIST, a basic helix-loop-helix transcription factor whose activation plays an essential role in EMT and cancer metastasis, is instead considered an indicator of tumour aggressiveness." (PMID 28977999, 2017). "Co-labeling studies showed that tumor cells and reactive astroglia, but not immune cells contribute to the ZEB1 positive population." (PMID 28945795, 2017). "The later identification of Zeb1/2 and other basic helix-loop-helix (bHLH) transcription factors as inducers of EMT and potent repressors of E-cadherin in tumor progression strongly suggested that the same molecules are used to trigger EMT during embryogenesis and tumorigenesis." (PMID 26985909, 2016). "They identified seven miRNAs, miRs-300, -382, -494, -495, -539, -543, and -544, located in this region that serve as tumor suppressors by cooperatively repressing an EMT signaling network comprising TWIST1, BMI1 polycomb ring finger proto-oncogene, ZEB1/2, and the miR-200 family." (PMID 26784241, 2016). "Tumor cells along with progression of EMT assume a spindled shape, lose desmosomes and adherence junctions, and express mesenchymal molecules such as microtubule vimentin and a zinc-finger E-box transcription factor ZEB-1/TCF8." (PMID 27622654, 2016). "During tumor metastasis, several signaling pathways (e.g., AKT, Wnt and NF-kB) contribute to EMT and cell invasion by activating transcription factors SNAIL, SLUG and ZEB1." (PMID 27806330, 2016). "Redistribution of E-cadherin and strong up regulation of ZEB1 and Vimentin were observed in the surviving tumor; indicative of epithelial to mesenchymal transition (EMT), a mechanism that could contribute to tumor resistance." (PMID 27460820, 2016). "HOTAIR also regulates BCSCs, and microarray analysis reveals HOTAIR overexpression upregualtes the genes related to stemness and EMT, such as CD44, STAT3, ALDH2, ZEB1 and VIM, but the tumor initiating frequency in vivo assay are needed to demonstrate the role of HOTAIR in regulating BCSCs further." (PMID 26349457, 2016). "As a master EMT regulator, the Zeb1-miR-200 double-negative feedback loop has been shown by multiple groups to play a prominent role in tumor invasion and metastasis." (PMID 26728244, 2016).
tumor (continued). "Moreover, HULC contributes to ZEB1-induced epithelial-mesenchymal transition (EMT), a requirement for tumor invasion and metastasis that plays a key role in cancer progression." (PMID 27285757, 2016). "Additionally, across the TCGA datasets (n = 9105 tumor specimens), CRKL levels negatively correlated with the miR-200 family levels, positively correlated with the expression of ZEB1, an EMT gene expression signature, and the p-Src Y416 levels." (PMID 26728244, 2016). "Whereas ZEB1 is widely accepted as one of the most important activators of EMT and recently revealed as a mediator of tumor radioresistance and drug resistance, the role of FLASH in solid tumors' growth and dissemination is unknown." (PMID 27526108, 2016). "A self-enforcing feed-back loop that employs CD44s to activate Zeb1 expression renders tumor cell stemness independent of external stimuli, since Zeb1 further promotes CD44s isoform synthesis." (PMID 26985909, 2016). "Zeb1 expression was complementary with that of class III beta-tubulin/Tuj1, an early neuronal differentiation marker, indicating that Zeb1 expression is extinguished in both normal and tumor-derived cells proceeding toward the differentiated phenotype." (PMID 27178982, 2016). "On the contrary, ZEB1 expression seems to decrease in tumour versus normal (median log2 expression value from 7.6 of normal to 6.9 of tumour and 6.6 of metastasis)." (PMID 27463018, 2016). "Moreover, ZEB1 and ZEB2 were significantly higher expressed in HCC tissues than adjacent non-tumor tissues." (PMID 27861158, 2016). "This revealed that these tumour cells contain abnormally high levels of Zeb1, and so do not take on a polarized form." (PMID 27178982, 2016). "While vemurafenib did not affect tumor growth of control resistant cells, ZEB1 inhibition alone or in combination with vemurafenib led to a significant decrease in tumor growth." (PMID 27596438, 2016). "ZEB1 is predominantly known for its EMT promoting activity, as well as for driving tumorigenesis and metastasis by induction of stemness properties in the tumor cells." (PMID 25973542, 2015). "We detected ZEB1 in PDAC samples in stromal cells within desmoplastic areas, but epithelial tumor cells did not express ZEB1." (PMID 25910082, 2015). "However, an inverse correlation was observed between the expression levels of miR-200b and ZEB1/2 in both ESCC cell lines (n = 7, P < 0.05) and ESCC tumor samples (n = 88, P < 0.05)." (PMID 26334393, 2015). "Moreover, miR-205-5p and members of the miR-200 family target epithelial-mesenchymal transition regulators (ZEB1 and SIP1), apparently being important in tumor progression." (PMID 26057471, 2015). "Furthermore, the bevacizumab-treated tumor contained significantly more tumor cells that stained for the EMT markers matrix metalloproteinase 2 (MMP2), Zinc-finger E box-binding homeobox 1 (Zeb1), Zeb2, Snail, Slug and Twist." (PMID 25957416, 2015). "Tumor cell invasion, dissemination and metastasis is triggered by an aberrant activation of epithelial-to-mesenchymal transition (EMT), often mediated by the transcription factor ZEB1." (PMID 25973542, 2015). "Our work suggests that Siah may be acting as a tumor suppressor in the context of EMT and metastasis via suppression of Zeb1." (PMID 25528765, 2015). "Furthermore, we found a strong linkage between ATDC overexpression, EMT, and tumor invasion and found that ATDC colocalized with Snail1 or Zeb1 in not only AKC and ALGSLKC mice but also early PanIN lesions from KC mice and human pancreatic tissues." (PMID 25593307, 2015). "ZEB1 is an activator of the EMT and has crucial roles in tumor progression towards metastasis." (PMID 24454732, 2014). "Since MiR-200s have been demonstrated to act as a tumor suppressor by suppressing Zinc-finger enhancing binding transcription factors (ZEB1 and ZEB2) to increase the E-cadherin in cancer cells, we measured ZEB1 levels from the samples of reporter assays." (PMID 24918286, 2014).
tumor (continued). "It has subsequently been shown to be involved in a broad range of regulatory processes, including EMT, tumor metastasis, development, and differentiation, providing a rationale as to why homozygous Zeb1 null mice are not viable." (PMID 25163748, 2014). "Consistent with the western blot results, the expression of TGF-β, Vimentin, ZEB-1 and N-cadherin detected by immunohistochemistry assay was also remarkably decreased, whereas the expression of SMAD-7 and E-cadherin was notably increased in the tumor tissues." (PMID 24625224, 2014). "More specifically, when comparing tumor versus normal, the observed significant upregulation of miR-200b leads to significant downregulation of the transcription factor SNAI2 (SLUG) and to a consequent downregulation of ZEB1." (PMID 24968068, 2014). "ZEB1 and MYB may therefore act as biologic switches, translating molecular changes in the tumor microenvironment into alterations in cell state." (PMID 24283570, 2013). "In the present study, a tumor cohort of 22 NPC and 7 normal cases (chronic inflammation only) were investigated and the expression of AKT was demonstrated to positively correlate with the expression of ZEB1." (PMID 24179501, 2013). "Comparison of the EMT gene-expression profiles in control versus ZEB1 knockdown PMC42-ET cells (part iii) may provide insights into specific gene-expression changes that may occur during MET at the secondary tumor site." (PMID 24283570, 2013). "Survival analysis was not significant for any subclass when stratifying tumour specimens into molecular subclasses, but in all cases ZEB1 negative tumours showed longer survival than ZEB1 positive specimens." (PMID 23818228, 2013). "Invasion is a common feature of brain malignancies from WHO grade II onwards, and we find ZEB1 expressed in invasive tumours (grade II–IV), but not in non-invasive neoplasms (grade I, data not shown)." (PMID 23818228, 2013). "Curiously, although immunofluorescent analysis of xenografted tumours indicated that invasive tumours lacked N-cadherin, Western analysis revealed that overall N-cadherin protein levels did not change between ZEB1 knockdown and controls." (PMID 23818228, 2013). "The ZEB1 expression level was not correlated with age, gender, tumor size, histological type, depth of invasion, tumor location, lymph node metastasis or lymphatic invasion." (PMID 23420790, 2013). "Immunoblot analysis of common pathway aberrations in these subclasses and other subclass markers revealed clustering of ZEB1 in the proliferative subclass, while ZEB1 negative tumours were slightly enriched for mesenchymal and proneural subclasses." (PMID 23818228, 2013). "Therefore, via regulating the expression of E-cadherin by targeting ZEB1 and ZEB2, miR-200a can inhibit the invasive potential of tumor cells." (PMID 22211245, 2012). "The most well-known function of the miR-200 family and miR-205 is their ability to regulate the expression of E-cadherin transcriptional repressors ZEB1 (also known as δEF1) and SIP1 (also known as ZEB2), factors important for epithelial mesenchymal transition (EMT) and tumor metastasis." (PMID 22514717, 2012). "ZEB1 expression was studied so far only in a small number of PDAC patients, where a reduced expression was found in patients following a complete resection with no tumor recurrence, in line with the fact that ZEB1 is expressed by poorly differentiated tumors." (PMID 23227088, 2012). "Reduced ZEB1 expression correlated significantly with lack of tumor recurrence after complete resection." (PMID 24281218, 2010). "Therefore, in a tumor microenvironment, increased TGF-β levels are thought to result in an increase of ZEB1 transcription to a point where it can overcome the repression caused by miR-200c." (PMID 20049172, 2010). "Therefore ZEB1 expression usually correlates with EMT features, high tumor grade and poor prognosis." (PMID 24281177, 2010).